KRAS (KRas proto-oncogene, GTPase)
Diseases named in the same sentence as KRAS in open-access papers (continued):
Sharing a sentence is not in itself a finding about the gene and the disease.
cancer (continued). "To further validate the induction of GGCT by Ras signaling, we knocked down KRAS gene in human cancer cells and observed that GGCT transcription is down-regulated." (PMID 31400748, 2019). "ANXA2 and KRAS were also direct downstream targets of miR-206 that modulated cancer cell growth, metastasis, and lymphangiogenesis in PDAC." (PMID 30700038, 2019). "KRAS, together with HRAS and NRAS, are members of the RAS family of small GTPases and mutations of these RAS genes are associated with one third of human cancers." (PMID 31208154, 2019). "As such, oncogenic KRAS is established as a driver of cancer initiation, progression, metastasis, therapy resistance, and immune suppression in multiple cancers." (PMID 31681587, 2019). "Ectopic expression of KRAS plasmid rescued the suppressive effects of miR-873 on cell proliferation and colony formation in both cancer cell lines." (PMID 30654191, 2019). "Given the critical role of oncogenic KRAS in controlling cancer metabolism, a growing number of studies have been focusing on targeting the metabolic vulnerabilities conferred by oncogenic KRAS." (PMID 30819189, 2019). "Based on these findings, we aimed to identify proteins associated with this resistance to MEK inhibition in KRAS and PIK3CA mutant cancers." (PMID 30944457, 2019). "The clinical importance of KRAS-driven alterations is not only awarded to how this oncogene favors cancer cells’ autonomous mechanisms but also to how it alters the way cancer cells interact and influence the TME components." (PMID 31847096, 2019). "KRAS as a typical oncogene for cancer initiation and progression has been proven in many cancer types, including CRC, with strong impact on early diagnosis, cancer progression, and prognosis." (PMID 31207989, 2019). "Identifying non-STAT3 downstream effectors/signaling pathways specifically mediated by LIF can be beneficial for evaluating therapeutic efficiency of LIF blockade in KRAS mutant cancers." (PMID 31296870, 2019). "We assessed the ability of a peptide based, oligonucleotide condensing, endosomolytic nanoparticle (NP) system to deliver siRNA to KRAS-driven cancers." (PMID 31413817, 2019). "While further work will be needed to determine if sodium channels are a direct consequence of KRAS overexpression, researchers have proposed ENaC should be targets for therapeutic intervention in various cancers." (PMID 31009485, 2019). "Despite being the most frequent oncogene in human cancer, KRAS has so far proven refractory to targeted inhibition." (PMID 31296870, 2019). "Oncogenic signals, including Myc, PIK3CA hotspot mutations (H1047R and E545K) and KRAS hotspot mutation (G12V), upregulate ATF4 to promote cancer survival." (PMID 31064130, 2019). "KRAS mutations represent another important genetic event in many cancer types; in CRC, studies on mutant KRAS mostly focused on changes in the molecular cargo of EVs and showed the selective packaging of some RNAs." (PMID 31028424, 2019). "Mutations in other conventional drivers (APC, KRAS, PIK3CA, ARID1A) were usually clonal within a carcinoma." (PMID 29991641, 2019).
cancer (continued). "The frequency of these mutations is higher in right-sided tumors, without any significant difference between unselected CRC and KRAS/NRAS/BRAF wt carcinomas." (PMID 31226844, 2019). "The growth patterns generated from the KRAS and BRAF mutated cells in 3D cultures revealed a resemblance to the putative anoikis-resistant subpopulations in actual carcinomas, including micropapillary structures and solid tumor cell islands." (PMID 31545494, 2019). "In contrast, KRAS, which is the most common mutant oncogene in cancers, is observed in about 25–30% of NSCLC patients." (PMID 29844447, 2018). "In cell‐based studies of NRAS‐ and KRAS‐mutant cancer cells, dabrafenib inhibited the NEK9 target CHK1, whereas vemurafenib did not." (PMID 29112787, 2018). "Next, we analyzed the dataset of the Cancer Cell Family Encyclopedia (CCLE) to further investigate the relationship between expression of transgelin-2 and KRAS mutation in PDAC cells." (PMID 30041673, 2018). "The mutant KRas in cancer cells accumulates in an elevated GTP-bound proportion and thus leads to a constantly activated Ras form." (PMID 29467941, 2018). "It is worth mentioning that the mutant KRas-driven cancer cells are more sensitive towards Spiclomazine than the wild-type KRas cancer cells." (PMID 29467941, 2018). "Together, these findings suggest that in mutant KRas-dependent human cancer cells, inactivating GSK3α/β induces apoptosis in a β-catenin- and c-Myc-dependent manner." (PMID 30514931, 2018). "When we also checked for KRAS amplification, K-Ras4B expression seemed to have correlations with KRAS amplification in each cancer type unlikely proportions of both K-Ras isoforms." (PMID 29504894, 2018). "KRAS is mutated in nearly a quarter of a wide spectrum of cancers, NRAS is mutated in <10% of cancers, but at a high frequency in specific cancers, while HRAS is rarely mutated in any cancer." (PMID 30194290, 2018). "This provides hope for the development of safer alternative treatments for KRAS(+) cancer patients owing to the specific-targeting nature of vaccines mediated by the immune system." (PMID 30042874, 2018). "In HepG2 and MHCC97L cancer cells, miR-30a overexpression completely blocks the activation of the KRAS/ERK pathway by directly binding the 3′-UTR of KRAS." (PMID 29535681, 2018). "The recent finding that inhibitors of the protein-protein interactions of the phosphopeptide-binding Polo-box domains of Polo-like kinases can be used to target KRAS mutant cancers speaks to the future therapeutic potential for such a strategy." (PMID 29606576, 2018). "This contrasts other types of cancer where KRAS and YAP share a high proportion of target genes and are interchangeable." (PMID 30353028, 2018). "From these discovery efforts, we derived a panel of recombinant antibodies to half a dozen of these differentially expressed targets, and applied the antibodies to confirm their surface expression patterns in a panel of mutant KRAS-driven cancer cell lines." (PMID 29359686, 2018). "KRAS-mutant cancer cells are shown to respond to host provided IL-1β in the pleural space by increasing non-canonical IKKα-RelB pathway activity." (PMID 29445180, 2018).
cancer (continued). "The IF confirmed the expression of the human CD147 at the surface of A549 cells, and it is consistent with our previous findings showing that CD147 localizes at the surface of cancer cell lines expressing oncogenic KRas mutants endogenously." (PMID 29899869, 2018). "This is important as it has been suggested that the position and type of mutations in KRas influence the transforming capacity of mutant KRas proteins and drug responses of cancer patients." (PMID 30514931, 2018). "RAS proteins, encoded by three ubiquitously expressed KRAS, HRAS, and NRAS genes, are located downstream of EGFR and are frequently mutated in human cancers." (PMID 29682203, 2018). "More cycles of KRAS renaissance are to be expected as biologically relevant tools for the targeted specific immunological therapy of patients with KRAS mutant cancer." (PMID 30283732, 2018). "KRAS is notoriously undruggable, and proteasome and IKKβ inhibitors have yielded suboptimal results in mice and men with cancer." (PMID 29445180, 2018). "Reduction of PIP5K1A combined with trametinib reduced the number of viable cells more than either change alone in three of the five tested KRAS-mutant human cancer cell lines." (PMID 30194290, 2018). "Several previous studies have shown that the KRAS oncogene contributes to anchorage independence of cancer cells." (PMID 30509235, 2018). "The cell viability assays showed that cancer cell lines (MIA PaCa-2, CFPAC-1, Capan-1, and SW1990) harboring KRas mutations displayed a striking inhibition of cell survival in a dose-dependent manner." (PMID 29467941, 2018). "Based on previous reports ATC cancer cells are positive for BRAF V600E (8505C, SW1746, OCUT1) or KRAS G12R (CAL62) oncogenic mutation." (PMID 29435119, 2018). "Our results showed that TFEB does not affect macropinocytic uptake, but is responsible for lysosomal catabolism of internalized protein and maintenance of intracellular amino acid availability in KRAS-mutant cancer cells." (PMID 30400219, 2018). "The three canonical Ras proteins (KRas, NRas, and HRas) are mutated in a broad range of human cancers with KRAS, NRAS, and HRAS mutations accounting for ∼22, ∼8, and ∼3% of all cancers, respectively." (PMID 29282294, 2018). "Our findings emphasize the need for the development of new therapeutics targeting JUN activating kinases, TAK1 and JNK, to sensitize KRAS mutant cancer cells to MEK inhibitors." (PMID 30482246, 2018). "Here, we identify endogenous T cell responses in patients with cancer to 3 different recurrent oncogenic driver mutations: BRAF V600E, KRAS G12V and the ERBB2 (Her2) internal tandem duplication (Her2-ITD)." (PMID 30400835, 2018). "Mouse embryonic fibroblasts (MEFs) expressing KrasG12D and KRAS-mutant human cancer cells took up markedly higher levels of tetramethylrhodamine (TMR)-dextran than the corresponding wild-type cells." (PMID 30400219, 2018). "We tested 4 neoplastic organoids from individual patient T1, T5, T9 and T14 (all KRAS-mut); the non-cancer organoid N1 was used as control." (PMID 29986755, 2018). "Further, BM1 cancers had a KRAS-related expression signature whereas BM2 cancers correlated with cell cycle and checkpoint-associated gene expression." (PMID 30598662, 2018). "Unexpectedly, mutant KRas-driven cancer cells are more sensitive towards Spiclomazine than wild-type KRas cancer cells." (PMID 29467941, 2018). "We show how KRAS-mutant cancer cells utilize myeloid-IL-1β in order to activate IKKα and alternative NF-κB signaling and to by-pass IKKβ canonical NF-κB dependence." (PMID 29445180, 2018).
cancer (continued). "This can explain CaM’s role in KRAS-driven cancers, in line with genetically-engineered mouse models showing that oncogenic KRas can induce senescence or proliferation and differentiation, but is unable to induce full PI3Kα activation." (PMID 30269291, 2018). "Cell lines stably expressing RHEB Y35N exhibit cancer transformation properties similar to KRAS G12 V." (PMID 29320991, 2018). "Based on this, it is likely that conclusions regarding TBK1 sensitivity in KRAS-positive cells, as well as other cancers, will be dependent on factors that relate to the differentiation status of the cells in question." (PMID 30223576, 2018). "These include KRAS, HRAS and NRAS and a variety of different mutations that mirror those found in human cancers with the major RAS effectors such as CRAF, PI3K and RALGDS." (PMID 29989546, 2018). "Because mutations in KRAS are observed in >90% of PDAC1 and are likely to be clonal mutations present in the majority of cancer cells, they are often identified in plasma as a ctDNA benchmark for PDAC6,18–22." (PMID 30072705, 2018). "A further study examining overall survival associated with post-lung metastasectomy found that it was significantly worse for BRAF mutant compared to KRAS mutant and wild-type cancers." (PMID 30598662, 2018). "Transduction of oncogenic KRAS dramatically enhances TGF-β-elicited SNAI1 expression, and TGF-β induces SNAI1 more strongly in cancer cells harboring constitutively active KRAS mutations." (PMID 30127261, 2018). "In cancer generally, and particularly in PDAC and NSCLC, KRAS is one of the most frequently mutated oncogenes." (PMID 29721157, 2018). "In this regard, analysis of NSCLC cancer cell lines showed increased NOX1 mRNA levels in cell lines bearing LKB1 and KRAS mutations." (PMID 29915721, 2018). "Here, we show that dabrafenib is more effective at inhibiting the growth of NRAS‐mutant and KRAS‐mutant cancer cell lines than vemurafenib." (PMID 29112787, 2018). "For this reason, therapeutic approaches to overcome KRAS‐driven cancer have been studied for several decades." (PMID 29896883, 2018). "Consistent with previous results, TMR-dextran uptake was higher in KrasG12D MEFs and KRAS-mutant human cancer cells than in the respective wild-type controls." (PMID 30400219, 2018). "We discovered multiple mosaic-activating variants in 4 genes of the RAS/MAPK pathway, KRAS, NRAS, BRAF, and MAP2K1, a pathway commonly activated in cancer and responsible for the germline RAS-opathies." (PMID 29461977, 2018). "Comprehensive mining of published in vitro data revealed that simultaneous mutations in KRAS and SMAD4 are associated with cancer cell radioresistance." (PMID 30220971, 2018). "The degree to which these tumors depend on KRAS is still underinvestigation but these high occurrences make RAS one of the most important drug targets for cancer, including CRC." (PMID 29534749, 2018). "In cancer cells, commonly occurring missense mutations in three members of the RAS family genes (HRAS, KRAS and NRAS) result in their constitutive activation." (PMID 29891945, 2018). "In 2013, the relationship between testing status and distance to an NCI cancer center was much stronger for KRAS testing than for EGFR testing." (PMID 29554880, 2018). "KRAS-mutant cancer cells upregulate macropinocytosis to import extracellular proteins, which subsequently undergo proteolytic degradation in the lysosome." (PMID 30400219, 2018). "Kirsten rat sarcoma (KRAS)-driven cancer treatment is an important clinical need that remains largely unmet due to limited targeted drug efficacy of key downstream effectors, including MAPK and PI3K-AKT pathways." (PMID 29522507, 2018).
cancer (continued). "Other groups, including ours, have previously shown that CD147 plays an important role in the biology of KRAS-driven cancers." (PMID 29899869, 2018). "Collectively, these studies strongly indicate that S100A10 is a central player in facilitating uPA‐mediated cleavage of plasminogen in KRAS‐transformed cancer cells." (PMID 30009399, 2018). "In KRas mutant pancreas cancers, components of the MAS are used to convert glutamate-derived aspartate into malate, a substrate for NADPH production through malic enzyme." (PMID 30122553, 2018). "In a recent study, it was discovered that the down-regulation of ERRFI1 enhances resistance to MEK inhibition in KRAS mutant cancer cells." (PMID 29801473, 2018). "These experiments show that RHEB Y35N transforms normal cells into cancer cells similar to KRAS G12V." (PMID 29320991, 2018). "In summary, the road to discovering the first approved KRAS inhibitor is still long and winding, considering the genetic heterogeneity of KRAS-mutant cancers and the cell context." (PMID 29534749, 2018). "In KRAS-positive cancers, TBK1 involvement in regulating Akt/mTORC1 was found in cells with a mesenchymal phenotype." (PMID 30223576, 2018). "In agreement with this, our initial studies showed dabrafenib to be more effective at suppressing the growth of NRAS‐ and KRAS‐mutant cancer cell lines than vemurafenib." (PMID 29112787, 2018). "In the present study, we initially investigated the anti-cancer activities of krukovine in KRAS-mutated NSCLC cell lines, as well as KRAS wild type cancer cell line and normal lung cell." (PMID 30186180, 2018). "KRAS, which belongs to the canonical RAS family, is the most frequently mutated proto-oncogene, accounting for 90% of cancer-associated mutations." (PMID 30352075, 2018). "In contrast, a treatment consisting of 22 Panitumumab injections, given at the regular rate, reduces the number of wild-type cancer cells, but the number of KRAS-mutant cells increases to the maximum carrying capacity, leading to treatment failure." (PMID 35847834, 2018). "RHEB Y35N cell lines appear to have a growth curve very similar to the KRAS G12V cell lines, indicative of transformed cancer cell lines." (PMID 29320991, 2018). "This interaction was validated at the endogenous level in three other KRAS-mutant human cancer cell lines." (PMID 30194290, 2018). "In this study, we demonstrated that TFEB plays a pivotal role in acquisition of nutrients required for growth in KRAS-mutant cancer cells under nutrient-depleted conditions." (PMID 30400219, 2018). "Increased rates of macropinocytosis in KrasG12D MEFs and KRAS-mutant human cancer cells were significantly attenuated by knockdown of KRAS or treatment with a pharmacological inhibitor of macropinocytosis, 5-(N-ethyl-N-isopropyl)-amiloride (EIPA)." (PMID 30400219, 2018). "Considering the key role this driver oncogene plays, the pharmacological drugging of KRAS remains a key challenge for cancer research." (PMID 29534749, 2018). "The timing (6 years later), the stage at onset, the KRAS mutation pattern and the MMR gene status were different between the cancers, but the different speed of progression was the most striking, and fatal, feature." (PMID 29915171, 2018). "In our study, we identified krukovine as a novel KRAS signaling inhibitor and evaluated its anti-cancer activity in NSCLC cell lines." (PMID 30186180, 2018). "Yeast has been specifically used to analyze the role of human KRAS in autophagy, a cancer-related process, and was established as a model to study KRAS-induced autophagy." (PMID 29463063, 2018).